NOD1 (nucleotide binding oligomerization domain containing 1)
Diseases named in the same sentence as NOD1 in open-access papers (continued):
Sharing a sentence is not in itself a finding about the gene and the disease.
infectious disease (6 papers, 2017 to 2024). A disorder directly resulting from the presence and activity of a microbial, viral, or parasitic agent in humans. "Another interesting study cited the relationship between NOD1 downregulation in neutrophils from periparturient dairy cows, the dysregulation of neutrophils, and their increased vulnerability to infectious diseases." (PMID 34066406, 2021). "Therefore, modulating the activity of NOD1 and NOD2 may potentiate immune response against infections or mitigate detrimental hyperinflammation in certain infectious diseases." (PMID 39329913, 2024).
cardiovascular disease (5 papers, 2020 to 2024). "NOD1 not only increases cardiovascular disease risk factors, but also mediates damage to cardiovascular endothelium, vascular smooth muscle, and myocardium." (PMID 39906040, 2024). "Our group and others have described a prominent role for NOD1 in the leading cause of death worldwide: cardiovascular diseases (CVDs)." (PMID 34066406, 2021). "However, a genome-wide association study has already shown that a rare variant of NOD1 is associated with intima-media thickness in patients suggesting a potential role for the NOD pathway in cardiovascular disease." (PMID 32588196, 2020). "Because both NETs and NET-related cell death or NETosis are considered a fundamental connection between innate immunity, inflammation, oxidative stress and cardiovascular diseases, this work aimed to study these mechanisms under the onset of NOD1 signaling." (PMID 35789437, 2022). "Notably, Rip2 and Nod1 may play additional roles in cardiovascular disease in addition to inflammation because they mediate angiogenic activity in endothelial cells." (PMID 39640499, 2024). "Finally, NOD1 activation under HFD conditions contributes to NETs formation and NETosis in the spleen, playing a role in splenic cells homeostasis and in the atheroma layer, further contributing to the development of cardiovascular diseases." (PMID 35789437, 2022).
inflammation (5 papers, 2014 to 2024). Aberrant reaction of the microcirculation characterized by movement of fluid and leukocytes from the blood into extravascular tissues. "Among these, NOD-like receptors (NLRs), including NOD1, NLRP1, and NLRP3, serve as vital interfaces between microbiota and systemic chronic inflammation." (PMID 38336763, 2024).
kidney (4 papers, 2020 to 2023). "NOD1 detects bacteria (bacterial peptidoglycan particles) and mediates production of inflammatory factors, and loss of NOD1 can accelerate stomach carcinogenesis in a mouse model." (PMID 38143746, 2023). "Cardiomyocytes from Nod1−/−-Nx and Rip2−/−-Nx mice showed a significant amelioration in Ca2+ mishandling without modifying the kidney impairment induced by Nx." (PMID 33238586, 2020).
adenocarcinoma (3 papers, 2017 to 2022). A common cancer characterized by the presence of malignant glandular cells. "Thus, SK3842 can also aggrandize tumorigenicity in some aggressive adenocarcinoma cells lines with enriched CSC sub-fraction through Nod1/Rip2 axis stimulation." (PMID 28300841, 2017).
renal disease (2 papers, 2018 to 2020). "The potential role of NOD1 in the cardiovascular complications caused by specific renal disease is unknown." (PMID 33238586, 2020).
respiratory diseases (2 papers, 2014 to 2025). "NOD1 deficiencies cause severe respiratory diseases and impair antibacterial mechanisms in mouse models." (PMID 25253572, 2014).
gastrointestinal disease (1 paper, 2017). A disease that occurs in the gastrointestinal system, excluding the hepatobiliary system. "This approach could be used for further investigation of LEPREL1 (chromosome 34) and NOD1 (chromosome 14) that were highlighted in a recent investigation of gastrointestinal disease in the Lundehund." (PMID 28570553, 2017).
NOD1 also shares sentences with these, for which no sentence is quoted: Salmonella Infections (4 papers); Arthritis (3); rheumatoid arthritis (3); squamous cervical cancer (3); allergic contact dermatitis (2); chronic kidney disease (2); Cognitive impairment (2); latent infection (2); liver (2); non-alcoholic fatty liver disease (2); oral squamous cell carcinoma (2); -dependent (1); Acidosis (1); allergic rhinitis (1); Alzheimer disease (1); and Muscular Disorder (1); atopic asthma (1); Atrophy (1); Bovine mastitis (1); brain glioma (1); Cerebral ischemia (1); cervical intraepithelial neoplasia (1); Chlamydia pneumonia (1); chronic obstructive pulmonary disease (1); chronic periodontitis (1); congenital heart disease (1); duodenal ulcer (1); eczema (1); epithelial neoplasm (1); esophageal squamous cell carcinoma (1).
A further 35 diseases each share a sentence with NOD1 in 1 paper.